IRF1 (interferon regulatory factor 1)
Diseases named in the same sentence as IRF1 in open-access papers (continued):
Sharing a sentence is not in itself a finding about the gene and the disease.
tumor (continued). "Sumoylated interferon regulatory factor (IRF)-1 competes with non-sumoylated IRF-1 to inhibit cytokine-mediated apoptosis, which results in tumor cell proliferation." (PMID 26317903, 2015). "Bevacizumab significantly decreased tumor volume in IRF1 down-regulated tumors (46.6±6.9 vs 9.0±2.6, P < 0.01), whereas tumor volume was not decreased by bevacizumab in control shRNA tumors (71.5±16.8 vs 42.0±11.1, P = 0.18)." (PMID 26362401, 2015). "Interestingly, IRF1 depletion in tumor cells significantly attenuated BV6-stimulated secretion of IL-8, IL-6, GM-CSF and MCP-1 by tumor cells." (PMID 25501823, 2014). "Taken together, these data demonstrate that IRF1 has a dual role in BV6-mediated signaling: It acts as a proapoptotic factor in cell death induction and also affects the interaction of tumor cells with their microenvironment by promoting the secretion of cytokines and attraction of immune cells." (PMID 25501823, 2014). "IRF-1 induces the expression of type-I IFN and acts as a tumor suppressor by inducing apoptosis." (PMID 25389759, 2014). "It is unclear, however, if the possible tumor-promoting activity of KPNA2 is due to its function as a nuclear transporter for selective immunoregulatory proteins such as STAT1 and interferon-γ-induced transcription factor IRF-1." (PMID 23536776, 2013). "As the expression of IRF1 is slightly down-regulated, we suspect that this may contribute to the growth of CLL tumor cells." (PMID 22427814, 2012). "The focus of the present study was to examine and compare IRF1 and IRF5 expression in human breast tissue and to determine whether IRF5 acts as a tumor suppressor." (PMID 22053985, 2011). "IFN signaling mediates tumor-suppressor effects and antiviral responses and is regulated by key transcription factors of the interferon-regulatory factor (IRF) protein family, including IRF1, IRF2, IRF3, IRF7, and IRF9." (PMID 22084693, 2011). "Compared to the constitutive expression of immune related networks in the tumor microenvironment, CPT-11 had an ambivalent effect with down regulation of several pro-apoptotic/pro-inflammatory transcripts including IRF-1 and, down-stream of it several interferon stimulated genes." (PMID 21569348, 2011). "Therefore, we established an irf-1−/− CN2 mouse model of persistent HCV expression, which allowed us to investigate the effects of HCV on lymphatic tissue tumor development." (PMID 22084693, 2011). "IRF-1 and IRF-3 have been shown to regulate TRAIL transcription in tumor cell lines." (PMID 19404407, 2009). "Furthermore, IRF-1 can inhibit downstream factors such as ZEB1, which may help suppress the epithelial-mesenchymal transition, migration, and invasion of tumor cells." (PMID 40909948, 2025). "We also observed that tumor cells that engaged senescence-related transcriptional programs, or “Sen-High” cells, upregulated IFN-γ signaling machinery, including Ifngr1, Ifngr2, Jak1, Jak2, Irf1, and Stat1, as well as IFN-γ target genes Cxcl9, Cxcl10, and Tap1." (PMID 40299790, 2025). "Furthermore, when xenograft mice were treated with CsnB in the presence or absence of IRF1, tumor tissues were prepared for IHC staining and western blotting, and the expression of Nur77 and IRF1 was evaluated." (PMID 38789431, 2024). "The tumor tissue slides showed all therapeutic groups contained sufficient amount of MNFs inside the tumor, and the remarkable therapeutic outcome can be attributed to the synergistic effects of GLUT-1 inhibition and the increase in IRF-1, which leads to downregulation of RAD51 expression." (PMID 38693181, 2024). "For instance, IRF1 functions in both myeloid and epithelial cells to counteract AOM/DSS-induced colorectal tumorigenesis, while RIPK3 activation in colon cancer cells leads to increased cytokine expression in the tumor microenvironment, contributing to robust cytotoxic anti-tumor immunity." (PMID 37398672, 2023).
tumor (continued). "The binding of IFN-γ to INF-γ receptors on tumor cell membranes activates Janus Kinase 1 (JAK1) and JAK2, which are signal transducers and activators of transcription (STAT) signaling that promote the expression of IFN-related genes, including interferon regulatory factor 1 (IRF1)." (PMID 37108802, 2023). "Given IRF1’s role as a negative regulator of proliferation and tumor suppressor in various cell types, we examined whether the absence of IRF1 affected HSC cell cycle distribution in primary steady-state mice." (PMID 37889967, 2023). "Our results not only support more broadly developing IRF1 as a biomarker predictive for the effectiveness of chemoradiotherapy, but also suggest investigating a combined pharmacological stimulation of RLR and IRF1 signaling as a potential adjuvant regimen in tumor therapy." (PMID 35436994, 2022). "In addition, we also found that the genes (GSDM, IRF1, GZMB, and CASP5, etc.)with a higher frequency of CNV have higher expression differences between normal and tumour tissues and greater correlation with prognosis, which further highlights the key role of CNV in GC." (PMID 35923703, 2022). "Overexpression of KPNA2 was previously reported in LUAD tissues and negatively regulated by a novel transcription factor interferon regulatory factor-1 (IRF1).47,48 Our study revealed that KPNA2 may be a proliferating marker and promote tumor progression in LUSC." (PMID 35027529, 2022). "Since the expression of IRF1 and MHC protein complex and IFN-γ-related genes is involved in the presentation of tumor antigens 49, down-regulation of their expression might be one of the mechanisms for tumor immune escape." (PMID 34093873, 2021). "Hence, the impact of BCA2 on NF-κB and IRF1, together with its roles in promoting the degradation of EGFR and c-Myc, suggests that BCA2 may play a tumor suppressive role." (PMID 34589482, 2021). "Although the effect of BCA2 on NF-κB in non-tumor breast cells was unexpected, the contrasting effects that BCA2 exerts on IRF1 made us hypothesize that this distinct regulation might help explain the current controversies on the role of BCA2 in cancer development." (PMID 34589482, 2021). "There was a negative correlation between IRF1 expression and tumor purity (r = .258, P = 1.24e-07)." (PMID 32925784, 2020). "Consequently, protein expression of IRF-1 was virtually absent in tumor cells cultured under OGD conditions." (PMID 31196219, 2019). "Our data suggests that rather than targeting IRF1 to reduce overall abundance – which would impede its tumour suppressive function, GSK3β-Fbxw7α aid in the timely clearance of DNA-bound IRF1 to support additional rounds of transcription and thus downstream phenotypes such as reduced proliferation." (PMID 30854564, 2019). "We hypothesized that high IRF-1 expression may reflect a tumor’s ability to benefit from anti-PD-1 therapy independent of its PD-L1 expression status." (PMID 28331615, 2017). "Secondly, the absence of measurement of other IRF family members, such as IRF-1, might have also influenced the findings of this study because they could have interactive effect on tumor progression." (PMID 28465494, 2017). "By identifying IRF1 as a key mediator of BV6-induced cell death and cytokine response, our study contributes to an improved understanding of factors that determine sensitivity to Smac mimetics and predicts implications on the tumor microenvironment and immune system." (PMID 25501823, 2014).
tumor (continued). "In conclusion, this identification of IRF1 as a dual regulator of BV6-induced apoptosis and inflammatory cytokine secretion provides novel insights into determinants of sensitivity towards Smac mimetic and possible implications of Smac mimetic treatment on tumor microenvironment and immune response." (PMID 25501823, 2014). "We have hypothesised that DNMTi can also act through the activation of the IFNγ-signalling pathway components and we therefore focused on the expression levels of the selected genes from this pathway, namely interferon responsible factors 1 (IRF-1) and 8 (IRF-8) and STAT-1 in tumour cells." (PMID 22015556, 2011). "Much of the early publications in identifying the role of IFNs was by using clonally derived specific cell types or global transcript sequencing of the entire tumor tissue, platforms that could not characterize collectively the expression levels of IRF1 in each cell type." (PMID 40862725, 2025). "However, since Hsp90 also chaperones some tumor suppressive proteins such as interferon regulatory factor 1, LATS1 and LATS2 kinases, shepherdin’s inhibition on Hsp90 might deregulate tumor suppressor pathways, which might be one of the reasons why shepherdin failed in clinical application." (PMID 32381104, 2020). "Importantly, IRF1 depletion impedes BV6-stimulated secretion of additional proinflammatory cytokines such as granulocyte–macrophage colony-stimulating factor (GM-CSF), IL-8, IL-6 and monocyte chemoattractant protein-1, and migration of primary monocytes to BV6-treated tumor cells." (PMID 25501823, 2014). "In contrast to FB2 fibroblasts, IRF1 was not expressed in the uncharacterized cell clusters, UNC1 and UNC4 in normal breast tissue, but it was upregulated in both clusters in tumor tissue." (PMID 40862725, 2025). "Most of these genes are not discussed in literature and their role in EBV infection and cancer is not clear, except for IRF1 and FAM3B, that function as tumor suppressor gene and oncogene, respectively." (PMID 40110195, 2025). "IRF1 demonstrated direct binding to VEGFR2 (but not VEGFR1), inhibited the PI3K/Akt signaling pathway and eNOS phosphorylation, and prevented tumor growth and angiogenesis in vivo." (PMID 38396830, 2024). "In a mouse model of EGFR-mutated lung adenocarcinoma, which has a non-inflammatory immunosuppressive tumor microenvironment, EGFR signaling recruits CD4+ regulatory T cells and CD8+ T cell infiltration by activating JNK/cJun and inhibiting IRF1." (PMID 38762484, 2024). "A previous study found that IRF1 was found to negatively regulate the function of CD4+CD25+ Treg cells by directly and specifically repressing the expression of FOXP3 gene, suggesting the negative correlation between IRF1 and FOXP3 in tumor immunity." (PMID 35664436, 2022). "Genes of the antigen-processing machinery and regulation (IRF1, IRF2, NF-κB1, NF-κB2, NLRC5, TAP1, TAP2, TAPBP) were not significantly expressed throughout all of the analyzed tumor transcriptomes." (PMID 35892842, 2022). "IRF1 and DTX3L induction by ATRA is specific, since it is not observed with other anti-tumor agents, as exemplified by the results obtained in HCC-1599 cells." (PMID 32384653, 2020). "SCC had significant correlations between IRF1 and eIF2α or ATF4 in the tumor but not in the normal tissue." (PMID 30305853, 2018). "IB assay of tumor tissues revealed that XAF1 induction leads to MMP9 reduction and strongly increases both cleaved PARP and CASP3 levels in sh-Control but not sh-IRF-1 tumors." (PMID 30042418, 2018). "In the same work, it was also found that up-regulation of IRF-1, but not IRF-2, leads to better tumor differentiation, enhanced lymphocyte infiltration, smaller tumor mass, and longer survival." (PMID 29599126, 2018).
tumor (continued). "Thus, increased hsa-mir-301a levels, decreased IRF1 mRNA levels, and their negative correlation were shown in LUSC tumor samples." (PMID 38927914, 2024). "However, unlike IRF1, IRF8 deletion did not change the expression of SLC3A2 or SLC7A11 in tumor cells." (PMID 36672246, 2023). "RT-qPCR results further depicted reduced expression levels of HDAC8 and SUCNR1 and enhanced IRF1 expression levels in the tumor tissues of mice treated with sh-HDAC8, whereas SUCNR1 expression levels were enhanced, and those of HDAC8 and IRF1 did not change after further oe-SUCNR1 treatment." (PMID 36035205, 2022). "Analysis of IRF1 locus copy number revealed the same physiological number of gene copies in MDA-MB-231 and T24 cells compared with non-malignant HEK293T cells, demonstrating that there is no genetic alteration at the IRF1 locus in these tumor cell lines." (PMID 25501823, 2014). "When both IRF1 and IRF2 were absent, type I IFN treatment could not restore MHC I expression or reverse resistance to CPI, confirming the concept that type I IFN can induce IRF1 and restore immunogenicity of the tumor cells and host cytotoxic response to them." (PMID 39281881, 2024).
infection (228 papers, 2008 to 2026). The state of being infected such as from the introduction of a foreign agent such as serum, vaccine, antigenic substance or organism. "For example, IRF1 was identified as a transcriptional modulator of ZBP1 because the level of ZBP1 is diminished in cells with IRF1 deficiency during infection." (PMID 41304245, 2025). "As expected, B cell-specific IRF-1 deficiency resulted in decreased anti-MHV68 IgG titers following WT MHV68 infection." (PMID 41263556, 2025). "Consistent with previous findings, we found that BMDMs deficient in IRF1 showed reduced cell death in response to infection with F. novicida." (PMID 37557956, 2023). "We found that IRF1-deficient cells had a lower susceptibility to infection following IFN-γ pretreatment, like control cells, for all viruses other than IAV, EMCV, and VSV, for which resistance was weaker than in control cells." (PMID 36736301, 2023). "The macrophage IRF8/IRF1 regulome was found required for protection against infection and is associated with chronic inflammation." (PMID 34290700, 2021). "Using a BEAS-2B respiratory epithelial cell line deficient in IRF1, we demonstrate higher susceptibility to infection with vesicular stomatitis virus (VSV) and influenza virus." (PMID 31156620, 2019). "More than 90% of the cells that were positive for nuclear IRF-1 harbored Mav associated with LAMP1+ membranes at all time points measured over the 3 days infection." (PMID 28806745, 2017). "IRF-1−/− → WT chimeras were capable of limiting infection and showed comparable susceptibility to WT → WT mice, suggesting that IRF-1 expression in WT host stromal and resident brain cells is critical to control the virus." (PMID 24675692, 2014). "Neurons from IRF-1−/− mice showed higher viral titers upon infection with VSV and were approximately two fold more susceptible than the WT neurons." (PMID 24675692, 2014). "Together, these findings suggested that the activation of IFN-γ/STAT/IRF-1 signaling was involved in the hepatic response to K. pneumoniae-caused infection." (PMID 24223208, 2013). "Studies with deficient mice have confirmed an important role for IRF-1 in controlling infection against EMCV or murine γ-herpesvirus 68 (γHV68)." (PMID 21909274, 2011). "The activity of the intact promoter upon infection was normal in IRF-1-deficient cells but strongly diminished in cells deficient in IRF-3 and -7, again consistent with an important role of IRF-3 in virus-induced up-regulation of Noxa." (PMID 21698224, 2011). "Moreover, infection with the M448R-deficient ASFV mutant leads to increased IRF1 protein stability and elevated expression of IRF1 target genes, including OAS1, OAS2, and ZBP1." (PMID 42262133, 2026). "Surprisingly, and in contrast to that observed during global IRF-1 deficiency, B cell-intrinsic IRF-1 expression was proviral, as evidenced by decreased splenic latent reservoir and germinal center response driven by wild-type MHV68 infection in mice with IRF-1-deficient B cells." (PMID 41263556, 2025). "Differential regulation of IRF1 by glucose/galactose is associated with infection outcomes." (PMID 39475961, 2024). "Similar levels of cell death and interleukin 18 (IL-18) release were observed in WT and IRF1-deficient BMDMs in response to infection with S. Typhimurium and P. aeruginosa, suggesting that IRF1 is dispensable for cell death and IL-18 release under these conditions." (PMID 37557956, 2023). "Notably, starting at 9 to 10 days post infection (dpi), severe disease in Irf1–/–mice was evident by rapid weight loss and high mortality rates." (PMID 36175404, 2022). "Moreover, the results presented in this study are the first to identify IRF1 as a factor associated with KSHV-susceptible samples that can influence the inhibitory activity of IFN-γ in the context of early infection of B cells." (PMID 36298850, 2022). "Indeed, the ability to govern events at the IRF1 line of defense contributes substantially to the outcome of pathogenic infections." (PMID 33476326, 2021).